DMBT1 (deleted in malignant brain tumors 1)
Description:
May be considered as a candidate tumor suppressor gene for brain, lung, esophageal, gastric, and colorectal cancers. May play roles in mucosal defense system, cellular immune defense and epithelial differentiation. May play a role as an opsonin receptor for SFTPD and SPAR in macrophage tissues throughout the body, including epithelial cells lining the gastrointestinal tract. May play a role in liver regeneration. May be an important factor in fate decision and differentiation of transit-amplifying ductular (oval) cells within the hepatic lineage. Required for terminal differentiation of columnar epithelial cells during early embryogenesis. May function as a binding protein in saliva for the regulation of taste sensation. Binds to HIV-1 envelope protein and has been shown to both inhibit and facilitate viral transmission. Displays a broad calcium-dependent binding spectrum against both Gram-positive and Gram-negative bacteria, suggesting a role in defense against bacterial pathogens. Binds to a range of poly-sulfated and poly-phosphorylated ligands which may explain its broad bacterial-binding specificity. Inhibits cytoinvasion of S.enterica. Associates with the actin cytoskeleton and is involved in its remodeling during regulated exocytosis. Interacts with pancreatic zymogens in a pH-dependent manner and may act as a Golgi cargo receptor in the regulated secretory pathway of the pancreatic acinar cell.
Synonyms: Gp-340; SAG; GP340; SALSA; muclin
Tractability: Antibody: its Gene Ontology location is reachable by antibodies, with high confidence; UniProt places it where antibodies can reach, with medium confidence; UniProt predicts a signal peptide or a membrane-spanning region.
Gene: Protein-coding gene on chromosome 10 (122,560,643 to 122,643,740, forward strand). Ensembl gene ENSG00000187908.
Subcellular location: Secreted
Subcellular location (Human Protein Atlas): Centriolar satellite; Predicted to be secreted
Pathways (Reactome):
Metabolism of proteins: Surfactant metabolism
Gene Ontology:
Molecular function: protein binding; calcium-dependent protein binding; pattern recognition receptor activity; scavenger receptor activity; zymogen binding
Biological process: defense response to Gram-negative bacterium; defense response to Gram-positive bacterium; epithelial cell differentiation; induction of bacterial agglutination; innate immune response; vesicle-mediated transport
Cellular component: cytoplasm; extracellular exosome; extracellular region; phagocytic vesicle membrane; extracellular matrix; non-collagenous component of interstitial matrix; zymogen granule membrane; membrane
Genetic constraint (gnomAD): Loss-of-function variants: 193 observed, 240.59 expected, observed/expected ratio (o/e) 0.8, 90% interval 0.71 to 0.9. The upper end of that interval is the gene's LOEUF score, 0.9, which puts it in group 3 of 6, group 1 being the genes least tolerant of losing a copy. Missense variants: 2,394 observed, 2,347.2 expected, observed/expected ratio (o/e) 1.02, 90% interval 0.99 to 1.05. Synonymous variants: 973 observed, 913.75 expected, observed/expected ratio (o/e) 1.06, 90% interval 1.01 to 1.12.
Homologues: Orthologues: chimpanzee DMBT1 (83% identical), mouse Dmbt1 (40% identical). Paralogues in human: CD163 (15% identical), CD163L1 (14% identical), SSC5D (14% identical), SCART1 (13% identical), PRSS12 (10% identical), SSC4D (10% identical), LOXL2 (8% identical), LOXL3 (8% identical), LOXL4 (8% identical), CD6 (7% identical), CD5L (6% identical), CD5 (5% identical), and 3 more.
Diseases named in the same sentence as DMBT1 in open-access papers:
DMBT1 is named in the same sentence as 114 diseases in open-access papers, as found by Europe PMC text mining. Sharing a sentence is not in itself a finding about the gene and the disease. The quoted sentences say what the papers report.
malignant brain tumors (24 papers, 2004 to 2025). "A putative tumor susceptibility gene DMBT1 (Deleted in Malignant Brain Tumors) has been identified in 10q25.3–26.2." (PMID 19653894, 2009). "On the other hand, the fold change of Dmbt1 (deleted in malignant brain tumors 1) was the lowest in Ang II–infused mice compared with control mice." (PMID 41226773, 2025). "The second most downregulated protein in high dysplasia regions compared to the region with normal epithelium and immune infiltration was “deleted in malignant brain tumors 1” (DMBT1), a known tumor suppressor involved in mucosal immune defense." (PMID 39252972, 2024). "The gene DMBT1 harbors homozygous deletions and/or lacks expression in malignant human brain tumors, and it was named deleted in malignant brain tumors 1 (Dmbt1)." (PMID 35743193, 2022). "In urothelial carcinoma, deletion of the gene SH3GL2 is known to promote malignant behavior, meanwhile while DMBT1 has been proposed as a tumor suppressor in brain cancers." (PMID 36352274, 2022). "COMP (cartilage oligomeric matrix protein) was identified as the most upregulated gene, whereas the most downregulated gene was DMBT1 (deleted in malignant brain tumors 1)." (PMID 33540589, 2021). "On the other hand, the expression of DMBT1 (deleted in malignant brain tumors 1) altered by <±5% (Fig. 5C1 and C2)." (PMID 30833641, 2019). "An example is Dmbt1, a gene usually deleted in brain cancers but induced in gastric precancerous lesions." (PMID 30621213, 2019). "Among the identified Tn antigen-modified glycoproteins, we found the known heavily N- and O-glycosylated mucin-like protein DMBT1 (deleted in malignant brain tumors 1)." (PMID 30305605, 2018). "DMBT1 (deleted in malignant brain tumor) was also one of the top 15 human KOs, its levels were quite abundant in most individuals." (PMID 27070903, 2016). "Using Mass Spectrometry (MS), we initially found that 22 proteins were differentially expressed and then validated deleted in malignant brain tumor-1 (DMBT1) and Ig lambda-2 chain C region (IGLC2) using Western Blotting." (PMID 25873979, 2015). "The protein deleted in malignant brain tumors (DMBT1) and the trefoil factor (TFF) proteins have all been proposed to have roles in epithelial cell growth and cell differentiation and shown to be up regulated in inflammatory bowel diseases." (PMID 23691218, 2013). "SNP41 and SNP137 are located in the coding regions of the solute carrier family 7 (anionic amino acid transporter), member 13 (SLC7A13) gene and Deleted in Malignant Brain Tumour (DMBT1) genes, respectively." (PMID 23691232, 2013). "It is also referred to as lung glycoprotein-340 (gp-340) and also as protein deleted in malignant brain tumors (DMBT-1)." (PMID 22605979, 2012). "Another protein with known functions in innate immunity and inflammation and therefore a possible role in dysregulated inflammation during CF is named DMBT1 (deleted in malignant brain tumors 1; alternative names: glycoprotein-340 (gp-340) or salivary agglutinin (SAG))." (PMID 35249163, 2022). "However, some LOH appear to be correlated with OS: 10q26, which carries DMBT1 (deleted in malignant brain tumours), is a possible tumour suppressor gene in glial tumours." (PMID 18506188, 2008).
brain tumors (20 papers, 1999 to 2026). "The DMBT1 gene shows frequent genomic rearrangements and/or loss of expression in two common types of malignant brain tumors, but also in diverse epithelial cancer types, including lung, gastric, esophageal, colon, breast, and skin cancer." (PMID 21614203, 2010). "Chromosome 10 harbors a number of important tumor suppressor genes including MMAC/PTEN (10q23) and DMBT1 (10q25), and loss of heterogeneity in this region could lead to tumorigenesis of primary brain tumors, especially primary GBMs." (PMID 34722888, 2021). "Among the upregulated secreted proteins in LvM16, nucleobindin 2 (NUCB2) and human deleted in malignant brain tumors 1 (DMBT1) ranked at the top." (PMID 40796724, 2025). "Spots M and Q were recognised as kallikrein‐1, and finally, spots R and S identified as deleted in malignant brain tumours 1 protein‐like (DMBT‐1)." (PMID 33981443, 2021). "DMBT1 (deleted in malignant brain tumors 1) was identified as the hub gene as it had the highest “betweenness centrality,” which describes the shortest-path connectors through a network." (PMID 32265914, 2020). "The salivary scavenger and agglutinin (SALSA), also known as gp340, “deleted in malignant brain tumors 1” (DMBT1) and salivary agglutinin (SAG), is a multifunctional molecule found in high abundance on human mucosal surfaces." (PMID 32098784, 2020). "Salivary agglutinin (SAG) and lung scavenger receptor glycoprotein (gp340) are multi-splicing products of Deleted in Malignant Brain Tumors 1 (DMBT1), a gene originally identified in brain tumors." (PMID 23815775, 2013). "Dmbt1 (deleted in malignant brain tumors 1) is downregulated 12.9 fold and is involved in the mucosal immune defense." (PMID 23300544, 2012). "Several studies have shown that the protein core of DMBT1SAG is identical with lung glycoprotein 340 (DMBT1GP340) and Deleted in Malignant Brain Tumors-1 (DMBT1)." (PMID 21614203, 2010). "This case-control study aimed to evaluate the expression of cystatin B (CSTB) and deleted in malignant brain tumor 1 (DMBT1) in the saliva of GC patients with healthy individuals to construct diagnostic algorithms using statistical analysis and machine learning methods." (PMID 35488257, 2022). "Furthermore, 2 proteins were in common between UF and SP + UF: Apolipoprotein A-I and deleted in malignant brain tumors 1 protein (DMBT1)." (PMID 32842715, 2020). "The protein is known by numerous other names, including salivary agglutinin, glycoprotein-340, and Deleted in Malignant Brain Tumors 1 (DMBT1), but the name SALSA was most recently proposed to unify the original discovery in saliva with the ability to scavenge and agglutinate bacteria." (PMID 31850379, 2019). "LARP4B and DMBT1 have already been reported as deleted in brain tumors." (PMID 29844869, 2018).
breast carcinoma (13 papers, 2004 to 2025). "A nearby SNP, rs2981745 (C>T) in 5′UTR region of DMBT1, has been reported to be associated with increased breast cancer risk and rs2981745-T has decreased promoter activity compared with rs2981745-C." (PMID 23107584, 2012). "Sequence analysis of a 5′ RACE product of DMBT1 demonstrated that rs2981745, a putative breast cancer risk locus, appears to be one of the causal variants leading to DASE in DMBT1." (PMID 23107584, 2012). "In murine breast cancer cell lines, Dmbt1 expression was also higher in the liver-tropic AT3 and Py8119 as compared to the less metastatic NF639 and 4TO7 cells." (PMID 40796724, 2025). "Some research has reported that tumors like esophageal carcinoma, colon carcinoma, bladder carcinoma, breast cancer, prostate carcinoma, and non-small cell carcinoma presented a lower expression of DMBT1 compared with normal tissues." (PMID 34422633, 2021). "DMBT1 (Deleted in malignant brain tumors 1 protein) (5.26-fold decrease) is a putative tumor suppressor gene frequently deleted in brain, gastrointestinal and lung cancers and down-regulated in breast cancer and prostate cancer." (PMID 24161199, 2013). "Using PCR and Sanger sequencing, we successfully validated the DASE predictions in this breast cancer-related network, which includes cancer causative genes ZNF331 and USP6, and breast cancer risk associated gene DMBT1." (PMID 23107584, 2012). "deleted in malignant brain tumors 1 (DMBT1) SNPs rs2981745 and rs11523871 significantly increased breast cancer risk only in women aged above 60 years." (PMID 22773901, 2012). "The redistribution and up-regulation of DMBT1 in normal and hyperplastic tissues flanking malignant tumours and its down-regulation in carcinomas suggests a potential role in breast cancer." (PMID 15301691, 2004). "DMBT1 expression was detected by RT-PCR in 13 of 35 (37%) infiltrating carcinomas and in 2 breast cancer cell lines." (PMID 15301691, 2004). "Concordant downregulation of DMBT1 in breast cancer supports its potential for cancer progression across stages and might be a new target for immune therapy." (PMID 35031021, 2022). "DMBT1 expression was downregulated at both protein and mRNA level in breast cancer." (PMID 33540589, 2021). "Expression of DMBT1 goes down in breast cancer, we observed a similar trend in our analysis." (PMID 31379917, 2019). "A similar correlation emerges for DMBT1, which is evidently involved in ulcerative colitis and in various cancer types (prostate cancer, breast cancer, glioblastoma, medulloblastoma and melanoma) and that here appears to be differentially expressed even among colon cancer and normal tissues." (PMID 23095257, 2012). "In a recent paper on breast carcinogenesis, qualitatively similar data were reported for DMBT1 in human breast cancer, but an indirect weak correlation between the degree of differentiation of the breast carcinomas and the extent of the immunoreactivity was found." (PMID 15301691, 2004). "In addition, it is also of interest to further analyze the mechanisms of DMBT1 upregulation in liver-tropic breast cancer, as this could provide more opportunities to specifically inhibit tumor-derived DMBT1." (PMID 40796724, 2025). "The discrepancy in the results between our and this study may be due to sampling problems, the size of the sample and heterogeneous expression of DMBT1 in breast cancer or to other poorly-defined factors such as race, age or hormonal status of the population under study." (PMID 15301691, 2004). "In addition, multiplex IF staining of human liver metastases of breast cancer confirmed the correlation of NETs with CD68+ cells, DMBT1 and CCL8 expression." (PMID 40796724, 2025). "Further analysis of their expression in human breast cancer samples of a published UNC dataset showed the association of DMBT1, but not NUCB2, expression with patient survival." (PMID 40796724, 2025).
breast carcinoma (continued). "DMBT1 mRNA was detected in both the breast carcinoma cell lines analysed: Hs 578T and T47D (not shown)." (PMID 15301691, 2004). "In addition, analysis of an in-house Qilu breast cancer cohort revealed higher DMBT1 expression in liver-metastatic breast tumors than non-metastatic tumors." (PMID 40796724, 2025).
medulloblastoma (12 papers, 2012 to 2024). A malignant, invasive embryonal neoplasm arising from the cerebellum. "DMBT1 gene deletion or loss of function is associated with tumor progression in glioblastoma, medulloblastoma, and lung, gastric, and colorectal tumors." (PMID 38260202, 2023). "For example, homozygous deletion of the DMBT1 gene on chromosome 10 (encoding Deleted In Malignant Brain Tumors 1 protein) has been reported in glioblastoma and medulloblastoma." (PMID 30967140, 2019). "DMBT1 (deleted in malignant brain tumor 1) is a putative tumor suppressor implicated in the carcinogenesis of medulloblastoma and glioblastoma." (PMID 29844869, 2018). "As observed in many other tumors, deletion of the DMBT1 gene is also noted (OMIM 601969) in medulloblastoma." (PMID 39022728, 2024). "Deleted in malignant brain tumor 1 (DMBT1) is a tumor-inhibiting gene located on chromosome 10q25.3-q26.1 to its inactivation in several medulloblastoma cell lines in comparison with normal cells." (PMID 35488257, 2022). "DMBT1 was originally identified as a tumour suppressor gene in medulloblastoma, whereas accumulating evidence confirms that DMBT1 produces effects in innate immunity and epithelial cell differentiation and binds to viral or bacterial pathogens." (PMID 32760201, 2020). "The gene Deleted in malignant brain tumors 1 (DMBT1) was first proposed as a candidate tumor suppressor gene because of its inactivation in several medulloblastoma cell lines, as compared with normal cells." (PMID 28423364, 2017). "For example, members of the cysteine-rich scavenger receptor family, DMBT1(10q25.3–26.1), are heterozygously absent in oligodendrogliomas, medulloblastoma, gastrointestinal cancer, and lung cancer." (PMID 34108028, 2021). "This putative tumor suppressor gene plays an important role in human medulloblastomas (OMIM 601969) and so far there is no described DMBT1 variant in humans associated with a congenital phenotype." (PMID 28768473, 2017).
Crohn disease (9 papers, 2010 to 2024). A gastrointestinal disorder characterized by chronic inflammation involving all layers of the intestinal wall, noncaseating granulomas affecting the intestinal wall and regional lymph nodes, and transmural fibrosis. "A deletion variant of DMBT1 has been previously associated with Crohn's disease, and a DMBT1−/− knockout mouse has increased levels of colitis induced by dextran sulphate." (PMID 26813944, 2016). "DMBT1 (deleted in malignant brain tumors 1) is overexpressed in epithelial cells and has been found associated with ulcerative colitis and Crohn’s disease." (PMID 22952805, 2012). "It has also been shown that there is an association of a Dmbt1 variant allele with Crohn's disease and there is a correlation of expression levels of Dmbt1 with inflammatory bowel disease severity." (PMID 20573196, 2010). "Indeed, a deletion variant of DMBT1 with a reduced number of scavenger receptor cysteine-rich domain coding exons is associated with increased risk of Crohn’s disease, and diminished SALSA function has been associated with Crohn’s disease." (PMID 38246944, 2024). "Moreover, some studies demonstrated that DMBT1 was associated with immune defense, cell polarization, differentiation and regeneration, autoimmune disease, and Crohn’s disease." (PMID 34422633, 2021). "DMBT1 is associated with innate immunity and autoinflammatory enteritis (Crohn’s disease)." (PMID 34422633, 2021). "Taken together, we show that the DMBT1 CNV does not affect susceptibility to Crohn's disease, at least in Northern Europeans." (PMID 26813944, 2016). "Similarly, an earlier study proposed association between Crohn’s disease and copy number defect at the gene DMBT1 but this was not confirmed in a later study with other cohort." (PMID 38246944, 2024). "It has been found that DMBT1 mRNA expression levels are elevated in tissues of adults with IBD (20 IBD biopsies and nine healthy controls) and correlate with both the Crohn’s Disease Endoscopic Index of Severity (CDEIS) for CD and the clinical activity index (CAI) for UC." (PMID 34828659, 2021).
colitis (8 papers, 2010 to 2022). Inflammation of the colon. "This is in good agreement with data showing that Dmbt1−/− mice were more susceptible to colitis and showed elevated mRNA levels for IL-6 and TNF during inflammation." (PMID 25885541, 2015). "In a DSS-induced colitis model, Dmbt1−/− mice were more susceptible to low doses of DSS than Dmbt1+/+ mice." (PMID 21614203, 2010). "Loss of DMBT1 in mice leads to enhanced dextran sulfate sodium–induced colitis." (PMID 32265914, 2020). "That DMBT1 has a direct involvement in inflammatory bowel diseases in vivo was shown in a mouse model where mice made deficient for DMBT1 were found to have an enhanced susceptibility to dextran sulfate sodium (DSS) induced colitis." (PMID 23691218, 2013). "Dmbt1-deficient mice for example, have enhanced susceptibility to dextran sulfate sodium (DSS)-induced colitis." (PMID 28423364, 2017). "A correlation of DMBT1-/- mice and colitis could be confirmed, in which elevated levels for IL-6 and TNF during inflammation could be seen." (PMID 34989914, 2022). "Similar to DMBT1, lack of SP-D in mice also showed increased susceptibility to dextran sulfate sodium–induced colitis." (PMID 32265914, 2020). "However, since this is a commensal bacteria induced colitis model, this effect is likely to be attributed to Dmbt1’s ability to control the natural intestinal microflora." (PMID 21614203, 2010).